DEFB1 (defensin beta 1)
Description:
Has bactericidal activity. May act as a ligand for C-C chemokine receptor CCR6. Positively regulates the sperm motility and bactericidal activity in a CCR6-dependent manner. Binds to CCR6 and triggers Ca2+ mobilization in the sperm which is important for its motility.
Synonyms: hBD-1; BD1; HBD1; DEFB-1; DEFB101; MGC51822
Tractability: Small molecule: a structure with a bound ligand is known. Antibody: UniProt places it where antibodies can reach, with high confidence; its Gene Ontology location is reachable by antibodies, with high confidence; UniProt predicts a signal peptide or a membrane-spanning region.
Gene: Protein-coding gene on chromosome 8 (6,870,592 to 6,877,936, reverse strand). Ensembl gene ENSG00000164825.
Subcellular location: Secreted; Membrane
Pathways (Reactome):
Immune System: Beta defensins; Defensins
Gene Ontology:
Molecular function: CCR6 chemokine receptor binding; identical protein binding; protein binding
Biological process: antibacterial humoral response; antimicrobial humoral immune response mediated by antimicrobial peptide; calcium-mediated signaling; defense response to bacterium; defense response to Gram-negative bacterium; defense response to Gram-positive bacterium; innate immune response in mucosa; positive regulation of flagellated sperm motility involved in capacitation; response to bacterium; chemotaxis; G protein-coupled receptor signaling pathway; immune response; innate immune response; defense response
Cellular component: extracellular exosome; extracellular region; membrane; microvesicle; sperm midpiece; Golgi lumen
Genetic constraint (gnomAD): Loss-of-function variants: 9 observed, 4.12 expected, observed/expected ratio (o/e) 2.18. That is too few expected variants to judge how well the gene tolerates losing a copy. Missense variants: 162 observed, 81.01 expected, observed/expected ratio (o/e) 2. Synonymous variants: 56 observed, 30.29 expected, observed/expected ratio (o/e) 1.85, 90% interval 1.45 to 1.97.
Homologues: Orthologues: chimpanzee DEFB1 (99% identical), macaque DEFB1 (93% identical), pig DEFB1 (59% identical), dog DEFB1 (57% identical).
Diseases named in the same sentence as DEFB1 in open-access papers:
DEFB1 is named in the same sentence as 148 diseases in open-access papers, as found by Europe PMC text mining. Sharing a sentence is not in itself a finding about the gene and the disease. The quoted sentences say what the papers report.
periodontitis (15 papers, 2009 to 2024). An acute or chronic inflammatory process that affects the tissues that surround and support the teeth. "The results of the present study indicate that the variant of rs11362 of the DEFB1 gene was associated with periodontitis and periodontitis with T2DM." (PMID 38169768, 2023). "The gene DEFB1 encoding for hBD-1 has been identified as a major periodontitis-associated gene with functions in local host defence but also seems to be an important factor in proliferation control of oral cancers." (PMID 23050799, 2012). "The objective of this study was to examine whether, among individuals with phenylketonuria and type 1 diabetes mellitus, those with the IL1B rs1143634 and/or DEFB1 rs11362 genetic variants exhibit a higher periodontitis risk compared to healthy controls." (PMID 38248068, 2024). "It has been speculated that human beta-defensins may contribute to the progression of periodontitis, given the influence of DEFB1 variants on peptide expression." (PMID 38248068, 2024). "Genetic variations in the DEFB1 gene could affect gene expression and increase the susceptibility to periodontitis by having reduced capability to attack the pathogens, hence leading to the disease." (PMID 38169768, 2023). "The present study determined the association between SNPs at the 5’ untranslated region (UTR) in the DEFB1 gene and susceptibility to periodontitis associated with type 2 diabetes mellitus (T2DM) and analyzed the effect of 5’ UTR polymorphisms on DEFB1 gene expression." (PMID 38169768, 2023). "Our study analyzed the effect of genetic variations in 5’ UTR (rs11362 (-20G>A), rs1800972 (-44C>G), and rs1799946 (-52G>A)) of the DEFB1 gene on the susceptibility to periodontitis associated with T2DM in the south Indian population and their influence on gene expression." (PMID 38169768, 2023). "Single nucleotide polymorphisms (SNPs) in the specific genetic loci of the DEFB1 gene and its expression level could confer a degree of risk or protection from periodontitis associated with diabetes." (PMID 38169768, 2023). "In addition, dysregulation of β-defensin production also contributes to oral disease as a single nucleotide polymorphism in DEFB1, the gene that encodes hBD-1, has been linked to cases of periodontitis." (PMID 26029470, 2014). "To date, specific genetic variations consistently associated with periodontitis in certain populations include those within ANRIL, COX2, IL1, IL10, and DEFB1 genes." (PMID 39650553, 2024). "In fact, these findings are contradicted by a recent study aiming to verify a link between DEFB1 and LTF polymorphisms and periodontitis." (PMID 37372382, 2023). "In the present study, the expression of the DEFB1 gene was downregulated in periodontitis and upregulated in periodontitis with T2DM patients compared to healthy controls but showed no statistical significance." (PMID 38169768, 2023). "DEFB1 gene expression was determined by real-time PCR in the study group comprising periodontitis (n = 20), periodontitis with T2DM (n = 15), and healthy controls (n = 20)." (PMID 38169768, 2023). "DEFB1 gene expression was downregulated in periodontitis and upregulated in periodontitis with T2DM patients when compared to healthy controls but was not statistically significant." (PMID 38169768, 2023). "Our study demonstrated that patients suffering from chronic periodontitis present more commonly with the 1654A/A genotype on the DEFB1 gene and the 159T/T genotype on the CD14 gene." (PMID 23046822, 2012). "The variants of rs11362 and rs1799946 of DEFB1 5’UTR polymorphisms might influence the susceptibility and progression of periodontitis." (PMID 38169768, 2023). "This research would then suggest that miRNA202 and its CC phenotype could have a role in the disease progression by down-regulating DEFB1, a gene known to be involved in periodontitis." (PMID 37372382, 2023).
periodontitis (continued). "From the SNP analysis, it can be inferred that the presence of SNPs at the 5’ UTR (rs11362 and rs1799946) in the DEFB1 gene may be an important predictive factor for periodontitis." (PMID 38169768, 2023). "The results showed that the expression of the DEFB1 gene was 59% downregulated (fold change = 0.41) for the AA variant genotype of rs11362 in periodontitis patients when compared with healthy controls, but it was not statistically significant (p = 0.07)." (PMID 38169768, 2023). "Within the limitations of the study, the present findings suggest that DEFB1 and CD14 gene polymorphisms are significantly associated with chronic periodontitis and could possibly be potential markers for assessment of risk for periodontal disease." (PMID 23046822, 2012). "Some genetic variation of the DEFB1 gene may lead to the variable expression of HBD1, which is associated with a higher susceptibility to bacterial colonization and leads to an increased risk of dental caries periodontitis and oral infections." (PMID 35110972, 2022). "The association between DEFB1 gene polymorphism and periodontitis could not be established in previous studies." (PMID 23046822, 2012).
prostate carcinoma (14 papers, 2008 to 2024). A carcinoma that arises from epithelial cells of the prostate gland. "Gene mutation of DEFB1 or cancer-specific loss of hBD-1 expression has been reported in basal cell carcinoma, renal cell carcinoma and prostate cancer." (PMID 24658581, 2014). "Moreover, recent evidence has indicated that reduced expression of DEFB1 is found in a high percentage of renal and prostate cancers, therefore suggesting that DEFB1 acts as a tumor suppressor gene." (PMID 18817538, 2008). "Hypermethylation of the gene promoters has been found to be associated with reduced expression of two human β-defensin genes (DEFB1 and DEFB4) in prostate cancer cells and oral carcinoma cells, respectively." (PMID 35529861, 2022). "Although the impact of DEFB1 in PAAD has not been proven, its specific deletion as the only innate immune gene with long-term balancing selection and heterozygote advantage promotes the development of kidney and prostate cancers." (PMID 38375157, 2024).
cystic fibrosis (12 papers, 2011 to 2025). Autosomal recessive disorder caused by pathogenic variants in the CFTR gene (cystic fibrosis transmembrane conductance regulator), which encodes a chloride and bicarbonate channel expressed in epithelial cells, and follow the diagnosis criteria. "DEFB1 is a defensin and is implicated in cystic fibrosis pathogenesis." (PMID 27462363, 2016).
chronic obstructive pulmonary disease (11 papers, 2006 to 2023). A chronic and progressive lung disorder characterized by the loss of elasticity of the bronchial tree and the air sacs, destruction of the air sacs wall, thickening of the bronchial wall, and mucous accumulation in the bronchial tree. "Previous studies have been conducted in attempt to elucidate possible mechanisms underlying DNA methylation-dependent regulation of DEFB1 in patients with PCa and chronic obstructive pulmonary disease (COPD)." (PMID 27835705, 2016). "Polymorphisms of the DEFB1 gene are associated with several diseases including chronic obstructive pulmonary disease (COPD), oral Candida infections, asthma, atopic dermatitis, and periodontitis." (PMID 23185513, 2012). "For example, among the 4 chronic obstructive pulmonary disease (COPD)–associated proteins shown in the network, TGFB1 is the direct target of HCoV-229E, and all 4 proteins (TGFB1, DEFB1, SNAI1, and ADAM33) interact with at least 1 SARS-CoV-2 target protein." (PMID 33156843, 2020). "Polymorphisms in the defensin-1 gene, defB1, have been associated with low oral colonization with Candida albicans, protection from HIV, chronic obstructive pulmonary disease and Crohn's disease." (PMID 22174673, 2011). "The hBD-1 gene (DEFB1) is a single copy gene with several SNPs that have been associated with the pathogenesis of some chronic inflammatory diseases, including asthma and chronic obstructive pulmonary disease." (PMID 24139179, 2013).
colon carcinoma (10 papers, 2015 to 2025). "DEFB1 is an antimicrobial peptide implicated in the resistance of epithelial surfaces to microbial colonization, which decreased in colon cancer specimens." (PMID 35603163, 2022).
asthma (9 papers, 2008 to 2024). "Earlier studies have elucidated an association between DEFB1 polymorphisms and the pathogenesis of asthma." (PMID 31881038, 2019). "Some observational studies also reported diverse but conflicting expression levels of DEFB1 in mouse asthma models and clinical trials." (PMID 31881038, 2019). "Deregulation of the expression human beta defensin 1 (DEFB1), an antimicrobial peptide, has been implicated in the pathogenesis of COPD and asthma." (PMID 23185513, 2012). "Among defensins, the human β-defensin 1 (DEFB1 [OMIM *602056]) promoter has been extensively studied since specific polymorphisms and haplotypes of it have been associated with asthma and atopy, susceptibility to severe sepsis, as well as HIV and Candida infection predisposition." (PMID 18817538, 2008). "However, the role of DEFB1 in the development and pathogenesis of asthma is unclear." (PMID 31881038, 2019).
oral squamous cell carcinoma (9 papers, 2012 to 2023). "For example, DEFB1 (encoding human ß-defensin-1 [HBD-1]), is a potential tumor suppressor which has been shown to participate in the innate immune response and can suppress tumor migration and invasion in oral squamous cell carcinoma." (PMID 33867351, 2021).
psoriasis (9 papers, 2009 to 2024). An autoimmune condition characterized by red, well-delineated plaques with silvery scales that are usually on the extensor surfaces and scalp. "We demonstrated that mRNA expression of hBD2 (DEFB4A) and LL-37 was significantly increased in TH17 cytokine-induced collagen-based psoriasis models compared with expression in untreated skin constructs, but expression of hBD1 (DEFB1) was not enhanced." (PMID 38251799, 2024).
dental caries (8 papers, 2009 to 2025). The decay of a tooth, in which it becomes softened, discolored, and/or porous. "This study represents the inaugural examination of the correlation between DEFB1 SNPs rs11362 and rs1799946 polymorphisms and the risk of dental caries in the Iranian population." (PMID 41195299, 2025). "This is the first report examining the association of DEFB1 SNPs with dental caries risk in the Iranian population." (PMID 41195299, 2025). "This research aimed to ascertain the correlation between DEFB1 SNPs rs11362 and rs1799946 and the susceptibility to dental caries in a southwestern Iranian population." (PMID 41195299, 2025). "This research is the inaugural report examining the potential association between DEFB1 polymorphisms and dental caries in Iranian adults." (PMID 41195299, 2025). "This study examined DEFB1 SNPs (rs11362 and rs1800972) in populations with high and low dental caries to ascertain the relationship between DEFB1 genetic polymorphisms and dental caries risk in the Iranian demographic." (PMID 41195299, 2025). "The DEFB1 gene encodes this peptide, which is the main defense against dental caries and is found in the mucosal surfaces of the gastrointestinal tract, urogenital tissue, salivary glands, and oral tissue." (PMID 41195299, 2025). "This study is the first investigation into the association between DEFB1 variants rs11362 and rs1799946 with dental caries risk in the Iranian population." (PMID 41195299, 2025). "This study aimed to examine the genetic association between the DEFB1 gene variants rs11362 and rs1799946 and dental caries in a case–control study." (PMID 41195299, 2025). "The functional polymorphisms of DEFB1 gene have been identified as potential markers for dental caries." (PMID 37928602, 2023). "Genetically, genes such as PRB4 and DEFB1 have been reported to be associated with the progression of dental caries due to variation." (PMID 37928602, 2023). "This study focused on PART1 rs27565 and DEFB1 rs11362 polymorphisms due to their previous potential association with dental caries." (PMID 36597064, 2023). "Carriers of the PART1 rs27565 TC + CC genotype and the DEFB1 rs11362 CT + TT genotype who ate sugary food more than once a week had a higher risk of developing dental caries." (PMID 36597064, 2023). "The aim of this study was to assess associations of PART1 rs27565 and DEFB1 rs11362 polymorphisms with the prevalence of dental caries in twelve-year-old children in Nandan County, Guangxi, China." (PMID 36597064, 2023). "The DEFB1 gene is linked to immune response, functioning as a host defense protein that impacts both the innate and adaptive immune systems, thereby influencing the progression of dental caries." (PMID 41195299, 2025). "Additionally, two meta-analyses indicated a correlation between DEFB1 variants and the risk of dental caries." (PMID 41195299, 2025). "Hence, we strongly advise conducting similar investigations on a larger sample size to validate whether DEFB1 SNPs, specifically rs11362 and rs1799946, indeed impact the expressions of this gene and contribute to the susceptibility of dental caries." (PMID 41195299, 2025). "Our objective was to determine if DEFB1 polymorphisms influence the early pathogenesis of disease and to assess the potential clinical significance of genetic testing for DEFB1 in the early detection and proactive management of dental caries." (PMID 41195299, 2025). "Herein, we designed a systematic review and meta-analysis to evaluate the association of DEFB1 (rs11362, rs1799946, and rs1800972) and MBL2 (rs7096206 and rs1800450) polymorphisms with the susceptibility to dental caries (DC) in children." (PMID 36832361, 2023). "The relationship between DEFB1 gene variants and dental caries in the Iranian population has not yet been investigated." (PMID 41195299, 2025).
dental caries (continued). "Aside from TUFT1 and DEFB1, the loci reported here have not been associated with dental caries in previous studies, which have largely comprised Caucasian individuals." (PMID 31533690, 2019).
Crohn disease (7 papers, 2010 to 2025). A gastrointestinal disorder characterized by chronic inflammation involving all layers of the intestinal wall, noncaseating granulomas affecting the intestinal wall and regional lymph nodes, and transmural fibrosis. "In this hypothesis, the low levels of circulating hepcidin could be a causative factor of liver autoimmunity, similar to the decreased expression of defensin DEFB1 that leads to impaired antimicrobial activity in patients with Crohn's disease." (PMID 26270641, 2015).
lung carcinoma (6 papers, 2019 to 2026). "A previous study showed that DEFB1 is a potential diagnostic biomarker for lung cancer." (PMID 33170151, 2020). "Furthermore, we developed multiple anti-DEFB1 monoclonal antibodies and found one of them, mAb-5, potently blocked DEFB1's function and inhibited lung adenocarcinoma progression in cell lines, organoids, xenografts, and spontaneous lung cancer models, while maintaining a favorable safety profile." (PMID 42009648, 2026).
renal cell carcinoma (6 papers, 2014 to 2023). "High expression of DEFB1 was reported to correlate with better prognosis in patients with renal cell carcinoma." (PMID 32953881, 2020).
Sepsis (6 papers, 2008 to 2025). Sepsis is defined as life-threatening organ dysfunction caused by a dysregulated host response to infection. "A candidate-gene case-control association study in a Chinese Han population showed that DEFB1 genetic variants were associated with susceptibility to sepsis and poor outcomes, suggesting that DEFB1 could be involved in the immune defense and inflammation response regulation during sepsis." (PMID 35345767, 2022). "Genomic variations in DEFB1 also contribute to the clinical course of severe sepsis and inflammation with presence of specific haplotypes associated with either increased susceptibility to, or protection from, severe infection and fatal outcome." (PMID 24139179, 2013).
candidiasis (5 papers, 2008 to 2015). Infection with the organism Candida. "Based on this observation, we assessed other members of the β-defensin family that have been linked to candidiasis, namely Defb1 and Defb4." (PMID 26317211, 2015).
liver cancer (5 papers, 2017 to 2024). An epithelial or non-epithelial malignant neoplasm that arises from the liver. "To investigate the mechanisms related to the downregulation of DEFB1 in liver cancer, we further analysed the 3 liver cancer patient cohorts to identify genes that had strong correlation with DEFB1 in terms of their mRNA expression." (PMID 29042578, 2017). "By using connectivity mapping, we have shown few chemicals, including ribavirin, anthracyclines and erlotinib, which were potential therapeutic agents for treating liver cancer, especially those with DEFB1 downregulated." (PMID 29042578, 2017). "The mRNA expression levels of DEFB1 and CDH1 were positively correlated in GSE25097 (r = 0.354, P < 0.001), GSE14520 (r = 0.348, P < 0.001) and GSE36376 (r = 0.381, P < 0.001) liver cancer patient cohorts." (PMID 29042578, 2017). "We found that only β-defensin 1, DEFB1, expression was consistently and significantly downregulated in liver cancer specimens compared to non-tumor specimens, but not that of other β-defensin genes." (PMID 29042578, 2017). "DEFB1 was also downregulated in liver cancer specimens compared to non-tumor specimens." (PMID 29042578, 2017).